RN7SL564P (RNA, 7SL, cytoplasmic 564, pseudogene)
Gene: Miscellaneous RNA gene on chromosome 6 (122,745,280 to 122,745,529, forward strand). Ensembl gene ENSG00000240606.
Homologues: Orthologues: chimpanzee Metazoa_SRP (95% identical), guinea pig Metazoa_SRP (66% identical). Paralogues in human: RN7SL2 (77% identical), RN7SL1 (76% identical), RN7SL3 (76% identical), RN7SL408P (74% identical), RN7SL769P (73% identical), RN7SL220P (73% identical), RN7SL333P (73% identical), RN7SL448P (73% identical), RN7SL7P (73% identical), RN7SL4P (72% identical), RN7SL680P (72% identical), RN7SL482P (72% identical), and 705 more.